MIR545 (microRNA 545)
Synonyms: hsa-mir-545; MIRN545; mir-545
Gene: MicroRNA gene on chromosome X (74,287,104 to 74,287,209, reverse strand). Ensembl gene ENSG00000207820.
Gene Ontology:
Biological process: cellular response to amino acid stimulus; long-term synaptic potentiation; response to bacterium
Homologues: Orthologues: macaque mml-mir-545 (100% identical).